ATP11C (ATPase phospholipid transporting 11C (ATP11C blood group))
Description:
Catalytic component of a P4-ATPase flippase complex which catalyzes the hydrolysis of ATP coupled to the transport of aminophospholipids, phosphatidylserines (PS) and phosphatidylethanolamines (PE), from the outer to the inner leaflet of the plasma membrane. Major PS-flippase in immune cell subsets. In erythrocyte plasma membrane, it is required to maintain PS in the inner leaflet preventing its exposure on the surface. This asymmetric distribution is critical for the survival of erythrocytes in circulation since externalized PS is a phagocytic signal for erythrocyte clearance by splenic macrophages. Required for B cell differentiation past the pro-B cell stage (By similarity). Seems to mediate PS flipping in pro-B cells (By similarity). May be involved in the transport of cholestatic bile acids (By similarity).
Synonyms: ATPIG; ATPIQ; HACXL
Tractability: Small molecule: a structure with a bound ligand is known. Antibody: UniProt places it where antibodies can reach, with high confidence; its Gene Ontology location is reachable by antibodies, with high confidence; UniProt predicts a signal peptide or a membrane-spanning region. PROTAC: ubiquitination databases record sites on it; its protein half-life has been measured.
Gene: Protein-coding gene on chromosome X (139,726,346 to 139,945,276, reverse strand). Ensembl gene ENSG00000101974.
Subcellular location: Cell membrane; Endoplasmic reticulum membrane; Early endosome membrane; Recycling endosome membrane
Pathways (Reactome):
Transport of small molecules: Ion transport by P-type ATPases
Gene Ontology:
Molecular function: ATPase-coupled intramembrane lipid transporter activity; phosphatidylethanolamine flippase activity; phosphatidylserine flippase activity; phosphatidylserine floppase activity; protein binding; ATP binding; ATP hydrolysis activity; magnesium ion binding; nucleotide binding
Biological process: phospholipid translocation; monoatomic ion transmembrane transport; aminophospholipid translocation; phospholipid transport
Cellular component: early endosome membrane; endoplasmic reticulum; endoplasmic reticulum membrane; lysosomal membrane; phospholipid-translocating ATPase complex; plasma membrane; recycling endosome membrane; recycling endosome; endomembrane system; membrane
Homologues: Orthologues: chimpanzee ATP11C (99% identical), macaque ATP11C (98% identical), rabbit ATP11C (97% identical), pig ATP11C (97% identical), dog ATP11C (96% identical), rat Atp11c (95% identical), mouse Atp11c (95% identical), guinea pig ATP11C (92% identical), tropical clawed frog atp11c (76% identical), zebrafish atp11c (70% identical), Drosophila melanogaster CG4301 (35% identical), Drosophila melanogaster CG9981 (30% identical), and 3 more. Paralogues in human: ATP11A (63% identical), ATP11B (55% identical), ATP8B2 (35% identical), ATP8B4 (35% identical), ATP10B (34% identical), ATP8A1 (34% identical), ATP8A2 (33% identical), ATP10A (33% identical), ATP10D (33% identical), ATP8B1 (32% identical), ATP8B3 (28% identical), ATP9A (27% identical), and 1 more.
Diseases named in the same sentence as ATP11C in open-access papers:
ATP11C is named in the same sentence as 16 diseases in open-access papers, as found by Europe PMC text mining. Sharing a sentence is not in itself a finding about the gene and the disease. The quoted sentences say what the papers report.
Hyperbilirubinemia (5 papers, 2017 to 2025). An increased amount of bilirubin in the blood. "For example, mutations in Atp11c in mice impair the hepatic uptake of organic anions, leading to hyperbilirubinemia and hypercholanemia as well as altered erythrocyte shape, anemia, and reduced erythrocyte lifespan." (PMID 40869043, 2025). "Mice deficient in ATP11C experience multiple abnormalities including hyperbilirubinemia, hepatocellular carcinoma, anemia, X-linked cholestasis and loss in B cell development supporting the importance of this P4-ATPase in liver and blood physiology." (PMID 30018401, 2018). "In addition, ATP11C may be important for bile acid transporter regulation since ATP11C deficiency leads to hyperbilirubinemia and hypercholanemia in mice." (PMID 34436325, 2021). "PKC controls the endocytosis of the P4-ATPase ATP11C (relates to B-cell maturation, erythrocyte shape, anaemia and hyperbilirubinemia), and phosphorylation of the ATP11C C-terminal region is required for endocytosis." (PMID 32719316, 2020).
acanthocytosis (1 paper, 2025). "XK and ATP11C preserve membrane integrity: XK loss causes McLeod syndrome with acanthocytosis and reduced deformability that may impair merozoite entry, while ATP11C-mediated phosphatidylserine flipping prevents premature PS exposure and macrophage clearance." (PMID 41450567, 2025).
Alagille syndrome (1 paper, 2022). "Genetic examination identified 11 cases of genetic disorders: Dubin–Johnson syndrome in 2, citrin deficiency in 2, Alagille syndrome in 2, trisomy 21 in 2, bile acid synthesis defects in 1, and two genetic variants of unknown diagnostic significance (e.g., ATP11C and ABCB11) in 2 patients." (PMID 36405823, 2022).
cholestasis (1 paper, 2012). Impairment of the bile flow caused by obstruction within the liver, or outside the liver in the bile duct system. "Mutations in the murine Atp11c gene leads to cholestasis and a striking B cell differentiation defect." (PMID 22912588, 2012).
ovarian insufficiency (1 paper, 2025). "Together, these data suggest FAM9C, ATP11C, and PAGE2B as potential candidate contributors to the ovarian insufficiency phenotype in TS and warrant further exploration." (PMID 40443572, 2025).
genetic disorders (2 papers, 2022 to 2024). "ATP11C and ATP11A have also been linked to inherited diseases." (PMID 38436085, 2024).
tumor (2 papers, 2020 to 2021). "Indeed, knockout of CDC50A, a subunit of ATP11C that participates in PS flipping, increases tumor-associated macrophages and enhances the effect of anti-CD47 blockade on limiting tumor growth." (PMID 32802188, 2020). "In addition, our data suggested that the expression levels of ATP11 C, CSE1L, SLC39A14, SLCO5A1, and GLS were higher in tumor tissues than in normal tissue by a factor of 3.4, 4.7, 2.8, 1.7 and 3.6, respectively." (PMID 34516344, 2021).
infection (1 paper, 2025). The state of being infected such as from the introduction of a foreign agent such as serum, vaccine, antigenic substance or organism. "NDV executes a biphasic regulation of ATP11c, modulating its function and expression to facilitate infection." (PMID 40812423, 2025). "To explore this, we monitored ATP11c protein levels over a 24-h infection time course." (PMID 40812423, 2025). "Collectively, these data establish ATP11c as an essential host factor driving NDV replication, with its activity predominantly critical during early infection stages." (PMID 40812423, 2025). "ATP11c overexpression significantly accelerated viral replication kinetics, whereas CRISPR–Cas9-mediated KO profoundly impaired viral gene expression, infectious particle production, and overall infection spread." (PMID 40812423, 2025).
ATP11C also shares sentences with these, for which no sentence is quoted: anemia (3 papers); breast carcinoma (1); citrin deficiency (1); Dubin-Johnson syndrome (1); hepatocellular carcinoma (1); lymphopenia (1); major depression (1); McLeod syndrome (1).